HSF1 (heat shock transcription factor 1)
Diseases named in the same sentence as HSF1 in open-access papers (continued):
Sharing a sentence is not in itself a finding about the gene and the disease.
cancer (continued). "Furthermore, we demonstrate that specific inhibition of HSF1 overcomes resistance to GPX4 inhibition and significantly increases the sensitivity of resistant cancer cells in vitro and tumors in vivo to ferroptosis." (PMID 34223704, 2021). "Furthermore, the same study demonstrated that HSF1 knockdown combined with HSP90 inhibition not only facilitated the degradation of oncogenic proteins, but also induced cancer cell apoptosis and decreased activity of the ERK pathway." (PMID 33525518, 2021). "We examined the relationship between the HSF1 expression and DSS in cancer patients." (PMID 34239690, 2021). "HSF1 is substantially overexpressed in various types of cancer and regulates the noncanonical transcriptional program, which is critical for tumor development and progression." (PMID 34917120, 2021). "Thus, considering the interplay between TG2 and HSF1 and their tumorigenic effect, a deep understanding of this axis in the complex and dynamic interplay between the tumor and its surrounding microenvironment could be of great importance to design new therapeutic approaches for cancer therapy." (PMID 34198675, 2021). "Furthermore, we interrogated the role and requirement of Akt signaling in TSP-4-mediated HSF1 activation facilitating the proliferation, EMT and cancer stemness of GBC cells." (PMID 33407730, 2021). "To prove that inhibiting Hsp70 may reduce EMT efficiency, we treated cells with a CL-43 inhibitor of the HSF1 transcription factor, which lowered Hsp70 and HSF1 content in the control and induced EMT in carcinoma cells." (PMID 34199046, 2021). "The strong ability of HSF1 and its mediated PSR to guard cellular proteostasis under stress conditions is critical for the survival, proliferation, metastasis, and development of drug resistance of cancer cells." (PMID 32110802, 2020). "Given the recent reports on other members of the HSF family influencing the growth and other properties of cancer cells, it will be important to conclusively map the genomic loci that are regulated by HSF2 and HSF4, either alone or in conjunction with HSF1 and other transcriptional regulators." (PMID 32408596, 2020). "How cancer cells instigate the expression of TGF-β and HSF1 in CAFs is another key question." (PMID 32331382, 2020). "Cancer cells actively remodeled the matrix as apparent by “holes” in matrix of 20-day AOM-DSS-treated WT mice but not in Hsf1 null matrix from the same time point." (PMID 33288768, 2020). "This may be explained by a cancer cell-type specific role of YY1, HSF1 and SP1 in regulating basal Ub gene expression." (PMID 32751694, 2020). "The respective roles of HSF1 in the stress response and cancer are thus complex and not fully explainable by the currently available data, although a thorough grasp of this area is essential for consideration of this factor as a target in cancer." (PMID 32331382, 2020). "Paclitaxel- and doxorubicin-resistant cancer cells showed higher expression of MDR1 and HSF1." (PMID 32457290, 2020). "HSF1 accumulation due to altered expression of a substrate-targeting subunit of the SCF (Skp-1-Cull-F-box) ubiquitin ligase complex, FBXW7, provides an advantage in cancer cells during disease progression." (PMID 32457290, 2020). "Because hsf1 mRNA level was not changed in drug-resistant cancer cells, post-translational modification of HSF1, such as phosphorylation patterns after paclitaxel treatment, was evaluated." (PMID 32457290, 2020). "Numerous small molecule drugs have therefore been developed that aim to reduce HSF1 activity, although most agents have not been shown to directly interact with HSF1 and have yet to show sufficient preclinical potential to enter the cancer clinic." (PMID 32331382, 2020). "In addition to HSF1, HSF2 is also overexpressed in Huh-7 and SMMC-7721 HCC cells, where it mediates extensive metabolic reprogramming that allows cancer cells to modulate their energy production requirements." (PMID 32408596, 2020).
cancer (continued). "Nevertheless, colonoscopy examination revealed significant inflammation in WT mice at day 20, but not in Hsf1 null mice, suggesting that HSF1 is required for the early inflammatory response that leads to cancer." (PMID 33288768, 2020). "These in vitro studies support the hypothesis that AOM-DSS induces HSF1 activation in fibroblasts, leading to formation of a pro-tumorigenic ECM that promotes cancer growth." (PMID 33288768, 2020). "Alternatively, HSF1-dependent fibrosis and ECM remodeling could be driving the transition from inflammation to cancer, in which case we would expect changes in the ECM to precede the appearance of tumors." (PMID 33288768, 2020). "While TGF-β and HSF-1 pathways have been already known as targetable in HNSCC by experimental means, our analyses provided a hint for the first time that the anti-cancer properties of crude neem leaf extract might function via these pathways." (PMID 30842898, 2019). "In none of the 45 histopathological cancer types, HSF1 expression displayed obvious linkage with HSPs genes." (PMID 31699156, 2019). "Therefore, one of the challenges in targeting HSP90 in cancer is to find compounds that specifically inhibit HSP90 without activating the HSR, or to use classical HSP90 inhibitors in combination with HSF1 inhibitors." (PMID 29710398, 2018). "Therefore, in the context of cancer, inhibiting the “normal” HSP90 function is beneficial; however, the consequent activation of the HSF1‐mediated transcriptional response feeds these oncogenic protein helpers (i.e., HSP90 and HSP70) into the same system." (PMID 29710398, 2018). "HSF1 has been considered a target for anti-cancer therapy due to the dependency of malignancies on this non-oncogene and its overexpression in many cancers." (PMID 30131848, 2018). "In addition, a new human HSF1 inhibitor, IHSF115, has been reported to impair the viability of several cancer cell via regulating the transcriptional activity of HSF1, but not by regulating HSF1′s DNA binding ability." (PMID 28914774, 2017). "Furthermore, since it has been shown that HSF1 and the AKT/mTOR cascade functionally interacts in other cancer types, we determined the levels of AKT and mTOR activity and correlated them with HSF1 activity in human HCC specimens (n = 64)." (PMID 28903330, 2017). "It is possible that in cancers with active HSF1, the increased levels of FN have a pro-invasion and survival effect and support cancer progression independent of the surrounding milieu." (PMID 29247221, 2017). "The reasons for this could be that inhibition of HSPs may trigger a protective heat shock response through activation of heat shock transcription factor 1 (HSF1) and GRP78, which blocks the apoptosis of cancer cells." (PMID 29299146, 2017). "Given evidences for the significant impairment of human malignant cell lines proliferation by knockdown of HSF-1 in contrast with minimal effect on normal cell line, HSF-1 could be a promising target for the cancer therapy." (PMID 29348836, 2017). "Studies have demonstrated that cancer specific alterations in signaling pathways for EGFR/HER2, ERK, insulin growth factor system may lead to HSF1 activation via post translation modification." (PMID 28914774, 2017). "In this manuscript, we have further shown that the IER5-mediated HSF1 activation can also occur in the absence of heat stress, and is highly important for proliferation of cancer cells." (PMID 26754925, 2016). "Furthermore, HSF-1, the master regulator of HSR, is believed to correlate with tumorigenesis and be the potential target of cancer therapy." (PMID 27105490, 2016). "In addition, in cancer cells that exhibit enhanced IER5 expression, suppression of IER5 by siRNA results in the downregulation of HSF1 activity and cell proliferation." (PMID 26754925, 2016). "Our initial attempts to create stable HSF1 knockdown in these cell lines were not successful, perhaps due to selective pressure for the cancer cells to re-express HSF1." (PMID 27997575, 2016).
cancer (continued). "Intriguingly the genetics of certain cancers have recently been ascribed to an HSF-1-dependent transcriptional program that is independent of stress." (PMID 26773049, 2016). "Considering the fact that HSF1 overexpression promotes HSP90 chaperone function in aneuploid cancer cells and the fact that CLL is characterized by one or more chromosomal abnormalities, we determined whether HSF1 is overexpressed in CLL." (PMID 26397138, 2015). "It was shown here that HSF1 directly activates miR-135b expression and thereby promotes HCC cell motility and invasiveness, demonstrating that miR-135b is a mediator of HSF1-induced cancer progression." (PMID 25537516, 2015). "In this paper, aneuploidy, a characteristic of most human cancers, seemed to be activated by HSF1, independent of its transcriptional activity such as HSP expression." (PMID 26359349, 2015). "Increased expression of HSF1 and HSP proteins, which is observed in several tumors and cancer cell lines, may lead to cancer chemo- and radio-resistance." (PMID 25944781, 2015). "Furthermore, the correlation between the HSF1 expression and HCC malignancies (including HCC metastasis, cancer cell differentiation, early phase HCC and late phase HCC, aging, gender and HBV infection) was studied." (PMID 25199534, 2014). "This included HSPA6, which is not upregulated in cancer cells addicted to HSF1, but is strongly upregulated during a bona fide heat shock response." (PMID 24516381, 2014). "Hsf1 regulates gene expression of heat shock proteins such as Hsp90, Hsp72 and Hsp27, as well as non-chaperone genes potentially utilized by cancers such as the tumour necrosis factor (TNF) receptor." (PMID 24675290, 2014). "Recently, it was shown that HSF1 is involved in the regulation of mRNA-binding protein ELAVL1 (HuR) which, in turn, controls mRNA stability and/or translation of many proteins involved in cancer." (PMID 24165036, 2013). "It is believed that the elevated expression of HSF1 in cancer cells does not lead to a kind of global “heat shock response”, but only specific members of the HSP family are induced in a tumor-dependent manner." (PMID 24212658, 2011). "In both cancer cell-lines, KU174 demonstrated a dose-dependent reduction in Hsp (Hsc70 and Hsp27), HSF-1 and client proteins (survivin Akt, Her2, nestin, CXCR4 and caspase-3) whereas, a minimal effect was seen on these proteins in normal RPTEC cells (data not shown)." (PMID 22039910, 2011). "HSF1 expression is likely to be crucial for the “non-oncogene addiction” and the stressed phenotype of cancer cells." (PMID 24212658, 2011). "But, the role of HSF1 in cancer far exceeds the sole regulation of Hsp genes since there is not always a correlation between the high HSF activation and/or expression levels frequently found in cancer cells, and those of HSPs." (PMID 24212658, 2011). "In this way, genetic knockdown of HSF1 fails to induce a decrease in the levels of HSPs in some cancer cell lines." (PMID 24212658, 2011). "In the absence of NK1R, the matrix Nkx2-5_02 had a predominant participation driving 8 transcripts, which includes those involved in cancer (EYA1, Trail, HSF1, and ELK-1), smooth-to-skeletal muscle trans-differentiation, and Z01, a tight-junction protein, expression." (PMID 17519035, 2007). "Consequently, HSF1 is the most studied HSF, and knowledge regarding its function has expanded beyond the HSR to include physiological and pathological processes, such as development, cancer progression, and neurodegenerative diseases." (PMID 40457168, 2025). "Future studies to further clarify the interaction of these two important transcriptional pathways in HSF1 and MYC, identify actionable therapeutic targets, and disrupt cancer-promoting pathways that could lead to clinical advances in a precision medicine therapeutic approach are warranted." (PMID 39831777, 2025).
cancer (continued). "Additionally, HSF1’s influence extends to cells of the TME by reprograming the stroma and influencing the invasion of immune elements, while indirectly facilitating the exportation of HSPs via exosomes, further emphasizing its significance in cancer biology." (PMID 40287736, 2025). "Cancer cells are known to undergo a metabolic shift from the preferential oxidative phosphorylation to aerobic glycolysis referred to as the „Warburg effect“ and HSF1 is not exempt from playing a role in this phenomenon." (PMID 40287736, 2025). "Importantly, HSF1 and HSF4 showed significantly higher expression in most cancer types." (PMID 39248163, 2024). "However, the mechanism of HSF1 regulating PD-L1 in cancer, especially in HCC, is still not fully clear." (PMID 36482717, 2023). "Although both HSF-1 and HIF-1 are essential transcription factors for stress responses, a limited number of studies have reported that HSF family proteins, HSF2 and HSF4, promote transcription of HIF-1α and result in VEGFA expression in several cancer cell lines." (PMID 38081808, 2023). "Thus, dual targetting of HSF1 and its upstream regulator DYRK2 may represent a novel approach to evade drug-resistance, and reduce cancer burden in vivo." (PMID 36622366, 2023). "Rockwell glycosylation plays an important role in cancer biology and rockwell glycosyltransferase IV (FUT4) is an essential enzyme that catalyzes the synthesis of Lewy’s oligosaccharides and is regulated by the specificity protein 1 (SP1) and heat shock factor protein 1 (HSF1) transcription factors." (PMID 36313365, 2022). "Additionally, significant correlations between HSF1 and immune checkpoint genes and the levels of B cells, CD8+ T cells, CD4+ T cells, macrophages, neutrophils, and dendritic cells have been detected in multiple kinds of cancers." (PMID 36069792, 2022). "It will be interesting to learn whether pro-longevity functions of HSF-1 that are independent of molecular chaperone induction, can improve neuronal proteostasis but not protect cancer cells from chronic proteotoxic stress." (PMID 35874276, 2022). "The differential upregulation of HSPs between non-transformed and cancer cells might depend on the different engagements of HSF1." (PMID 36195608, 2022). "A probable molecular basis for KRIBB11 priming cancer cells to apoptosis could include reduced expression of HSF1 target genes; this is apparently a potential mechanism, because the sensitizing effects of KRIBB11 were reproduced upon HSF1 silencing." (PMID 34299435, 2021). "Indeed, HSF1 is activated in CAFs where regulates at least two central signaling pathways, TGF-β and SDF1, with a transcriptional program completely different from the one used in the adjacent cancer cells." (PMID 34198675, 2021). "Moreover, inhibition of HSF1 does not lead to a decrease in the expression of HSPs in certain types of cancer, such as prostate cancer." (PMID 33808130, 2021). "Further analyses showed that the level of HSF1 did not affect the survival of ER-positive luminal A cancers but may slightly worsen the prognosis of basal-like cancers." (PMID 34783649, 2021). "Moreover, regardless of ER status, cancers with high HSF1 levels revealed a higher expression of MYBL1 than cancers with low HSF1 levels." (PMID 34783649, 2021). "Furthermore, hypoxia-activated HSF1 may augment the expression of MDR1, a membrane transporter whose expression is under the control of HSF1; if so, the overexpressed MDR1 may pump some small molecule radiosensitizers out the hypoxia-adapted cancer cell." (PMID 33806538, 2021). "Here, by using different cancer cell lines, including MCF-7, the authors showed that NRF2 could interact with two distinct AREs sites within the HSF1 promoter, inducing a marked increase in its mRNA and protein levels in response to oxidative or proteotoxic stress." (PMID 33805996, 2021).
cancer (continued). "HSF1 activation, in turn, might increase the transcription of BIS and HSP70 harboring HSE in the promoter, which exerts anti-apoptotic and protein quality control functions, providing a more pro-survival milieu for cancer cells." (PMID 33086735, 2020). "Therefore, targeting HSF1 translation could be a new strategy for the intervention of CRC and other cancers driven by activated WNT/β-catenin signaling." (PMID 32838807, 2020). "In general, HSF1, as a pleiotropic effect transcription factor, has selected many downstream molecules to participate in maintaining the proteomic stability of cancer cells and generate ‘Non-oncogene addiction’ of cancer." (PMID 32110802, 2020). "Considering that HSF1, HSF2, and HSF4 display multiple properties in cancer, which are either unique or common for each factor, or whether they act synergistically or antagonistically with each other, the need for new and improved agents targeting HSFs is significant." (PMID 32408596, 2020). "Interestingly, key evidence has emerged in recent literature that HSF-1 is playing an important role in transforming benign tumors into malignant, and therefore converting cancer cell to “non-oncogenic addiction”." (PMID 29682483, 2018). "Although there is no clinical investigation on inhibition of HSF-1 and demonstration of enhanced efficacy of cancer treatment, many preclinical studies, including our recent study, show promise for the potential to use as HSF-1 inhibitor as novel chemotherapeutic agents." (PMID 29682483, 2018). "Even a transient heat shock can promote cell migration in cancer cell lines, which may or may not depend on heat shock transcription factor 1 (HSF1)." (PMID 30224521, 2018). "In cancer, it has been shown that HSF1 could not be regarded as a canonical oncogene, as its overexpression cannot transform immortalized mouse embryonic fibroblasts (MEFs)." (PMID 28903330, 2017). "For example, high levels of HSF1 are found in cancer and correlated with negative outcomes." (PMID 28445500, 2017). "However, targeting both AKT and HSF1 can sufficiently reduce enough oncogenic functions that the cancer cell can no longer survive." (PMID 29088759, 2017). "Therefore, we compared the effects of Hsp90 inhibitor NVP-AUY922, HSF1 inhibitor NZ28 and HSF1 knockdown on the sensitivity of lung (H1339) and breast (MDA-MB-231, T47D) cancer cells to NK cell-mediated cytotoxicity and the expression of the NKG2D ligands MICA/B." (PMID 25854583, 2015). "However, constitutive activation of HSF1 does not fully explain HSP overexpression in cancer cells, because genetic knockdown of HSF1 fails to reduce HSP levels in many cancer cell lines to the normal basal levels seen in non-transformed cells." (PMID 26359349, 2015). "CA alone or combined with IR did not induce HSF1 or HSP70 expression in the cancer cell lines." (PMID 26029925, 2015). "Thus, further investigations of this new phosphorylation site on HSF1 and its predicted cell-cycle-dependent upstream kinase, CDK2, may lead to new insights on the role of this heat-shock protein in cancer." (PMID 26388441, 2015). "The exact mechanism by which CA regulated HSF1 and HSP70 in cancer cells remains unknown, but CA does not induce HSF1 or HSP70 in cancer cell lines." (PMID 26029925, 2015). "The ubiquity of HSF1 expression in different cancer cells might explain why celastrol has no cell-type limitation for HSP70 induction." (PMID 24589236, 2014). "However, it seems that further tumor progression does not depend on HSPs and a distinct HSF1-regulated transcriptional program is realized in cancer cells." (PMID 24467529, 2014).